ASNS (asparagine synthetase (glutamine-hydrolyzing))
Diseases named in the same sentence as ASNS in open-access papers (continued):
Sharing a sentence is not in itself a finding about the gene and the disease.
fibrosis (1 paper, 2018). the formation of excess fibrous connective tissue in an organ or tissue in a reparative or reactive process. "Finally, consistent with the relationship between ER stress, insulin resistance and liver fibrosis, ASNS expression, a transcriptional target of PERK, was significantly higher in animals with score 2 fibrosis when compared with score 1 animals (p<0.05)." (PMID 29897997, 2018).
Flavivirus Infections (1 paper, 2020). Infections with viruses of the genus FLAVIVIRUS, family FLAVIVIRIDAE. "Proteins differentially expressed in flavivirus infections other than Zika include SLC3A2, PODXL, ASNS and LPL." (PMID 32873194, 2020).
hepatoblastoma (1 paper, 2024). Hepatoblastoma (HB) is a malignant hepatic tumor and is the most common pediatric liver cancer. "In amino acid biosynthesis, GLUL and ASNS have been shown to correlate with overall survival during hepatoblastoma." (PMID 39684755, 2024).
lung squamous cell carcinoma (1 paper, 2020). "Interestingly, ASNS mRNA levels correlate with DENR•MCTS1 levels in individual cancer entities such as liver hepatocellular carcinoma (r > 0.35), lung squamous cell carcinoma (r > 0.5) and renal cancer (r > 0.49), and indeed throughout the entire TCGA pan-cancer set (r > 0.36)." (PMID 32938922, 2020).
osteosarcoma (1 paper, 2017). A usually aggressive malignant bone-forming mesenchymal neoplasm, predominantly affecting adolescents and young adults. "The results showed that CNOT1, ASNS, and EFHD2 were overexpressed in osteosarcoma tissues compared with normal tissues, suggesting that they might play an important role in the tumorigenesis of osteosarcoma." (PMID 28188704, 2017).
pancreatic adenocarcinoma (1 paper, 2021). "Eryaspase in combination with chemotherapy (gemcitabine) was associated with improvements in overall survival (OS) and progression-free survival (PFS), irrespective of asparagine synthetase (ASNS) expression in second-line advanced pancreatic adenocarcinoma." (PMID 33802156, 2021).
pancreatic cancer (1 paper, 2025). "In our work, we initially screened SU.86.86 and BxPC-3 pancreatic cancer cell lines, which exhibited low expression of ASNS." (PMID 41316157, 2025).
polycystic kidney disease (1 paper, 2018). A usually autosomal dominant and less frequently autosomal recessive genetic disorder characterized by the presence of numerous cysts in the kidneys leading to end-stage renal failure. "Based on this, we propose that inhibiting ASNS would be a much more specific way to reduce glutamine usage in polycystic kidney disease, opening an important opportunity for a more targeted approach in ADPKD treatment." (PMID 30480096, 2018).
prostate adenocarcinoma (1 paper, 2024). "The patients with high expression of ASNS and DDIT3 showed worse disease-free survival in patients with The Cancer Genome Atlas (TCGA)-prostate adenocarcinoma (PRAD) datasets." (PMID 38474084, 2024).
renal carcinoma (1 paper, 2020). A carcinoma arising from the epithelium of the renal parenchyma or the renal pelvis. "In agreement with this, in cancer entities where ATF4 activity (assayed as ASNS mRNA levels) correlates with survival (e.g. renal cancer and liver hepatocellular carcinoma), also DENR or MCTS1 levels have prognostic value." (PMID 32938922, 2020).
small cell lung carcinoma (1 paper, 2019). Small cell lung cancer (SCLC) is a highly aggressive malignant neoplasm, accounting for 10-15% of lung cancer cases, characterized byrapid growth, and early metastasis. "ASNS was also identified as a key target of the KRAS-ATF4 axis innon-small-cell lung cancer." (PMID 31188922, 2019).
ZIKV infection (1 paper, 2020). "Proteins previously identified to be differentially expressed during ZIKV infection include GAP43, DCX, PTPRZ1, ASNS, SLC3A2 and MKI67." (PMID 32873194, 2020).
tumor (79 papers, 2010 to 2025). "Among the 48 primary tumor samples, ASNS, CD40, CHD7, and ITPKB mutations were exclusively identified (n = 1 each; p = 0.0147) and were absent in the 67 metastatic samples." (PMID 40361470, 2025). "When the synthesis of asparagine is inhibited, it will hinder tumor growth and metastasis, and loss of ASNS expression will further increase the sensitivity of cells to asparagine depletion." (PMID 40781327, 2025). "ASNS expression is increased in HCC compared to the healthy liver, but its expression has decreased in parallel with the tumor stage, with low ASNS expression associated with poor prognosis." (PMID 37108625, 2023). "In CRC with mutated KRAS, the upregulation of ASNS enables the tumor to adapt to high glutamine demands." (PMID 36035152, 2022). "ASNS over-expression is associated with aggressive tumor growth, while ASNS knockdown inhibits growth in certain tumor models." (PMID 34065488, 2021). "ASNS inhibition also renders some types of tumour cells more susceptible to glutamine withdrawal-induced apoptosis, and asparagine addition sufficiently reverses this effect independent of TCA cycle anaplerosis." (PMID 32273511, 2020). "Since asparagine synthetase (ASNS) can catalyze the biosynthesis of L-asparagine by utilizing L-aspartate and L-glutamine as substrate, ASNS-deficient tumor cells were reported to be more sensitive to asparagine deprivation therapy." (PMID 29207624, 2017). "Overexpression of ABCB5 and ASNS has been linked to resistance to doxorubicin in different tumor types." (PMID 25810463, 2015). "It is particularly interesting that these examples of tumour-associated auxotrophy are centred around two reactions that utilise aspartate to synthesise other amino acids, both directly (ASNS and ASS1) and indirectly (GS, through regeneration of glutamine required for ASNS activity)." (PMID 31819187, 2020). "High levels of arginine lead to the upregulation of ASNS expression in tumor cells, and the upregulation of ASNS expression can further enhance the ability of cells to uptake arginine, creating a positive feedback loop." (PMID 39852139, 2025). "Endogenous aspartate production in tumor cells largely depends on the synthesis by asparagine synthetase (ASNS)." (PMID 40863132, 2025). "Adaptive expression of urea cycle enzymes ARG1/2, OTC, ASL and regulators like NAT10, which stabilizes ATF4 mRNA via ac4C modification to upregulate asparagine synthetase (ASNS) optimizing nitrogen utilization for tumor proliferation." (PMID 41179661, 2025). "The results showed that the expressions of ASNS, mTORC1 pathways (p-S6K, p-S6 and p-4EBP1) and Ki67 in the tumor tissues treated with CCT196969 were significantly lower than that in the control group." (PMID 40781327, 2025). "Meanwhile, knockdown of ASNS reduces MYC expression and tumor growth, implicating ASNS as a possible focus for cancer treatment." (PMID 40416363, 2025). "The deletion of ASNS in cells can lead to varying degrees of tumor cell apoptosis, autophagy, and cell cycle arrest." (PMID 40781327, 2025). "Mechanistically, the inhibition of METTL3 reduces the m6A level of asparagine synthetase (ASNS) mRNA, thereby downregulating ASNS expression and exerting anti-tumor effects." (PMID 40823087, 2025). "In response to therapeutic resistance mechanisms, tumor cells form adaptive escapes through ASNS and GAD metabolic branch activation, glucose/lipid metabolic compensation, and ATF4 transcriptional stress networks." (PMID 40598593, 2025).
tumor (continued). "In clinical NB cases, higher OGT, FOXC1, ASNS, GPT2, CBS, or FTH1 levels are correlated with worse survival, while lower ecircOGT or OGT-570aa expression is associated with tumor progression." (PMID 40416363, 2025). "In contrast, GPER1 was upregulated in the HCT116 ASNS−/− compared to HCT116 ASNS+/+ tumor xenografts in both male and female mice." (PMID 38886847, 2024). "Consistent with findings, the overexpression of ASNS has been correlated with tumor growth, poor clinical outcome, chemoresistance, and metastasis." (PMID 38474084, 2024). "The results showed that the expression of ASNS was correlated with the size of tumor growth,that of CEBPA was correlated with the gender of patients and TNM stage of tumor, and that of CAD was highly correlated with recurrence and metastasis." (PMID 35174151, 2022). "The expression of ASNS and CEBPA in tumor tissues of Group 1 was higher than that in non-tumor normal tissues, while the expression of ASNS and CEBPA in tumor tissues of Group 2 was lower than that in non-tumor normal tissues." (PMID 35174151, 2022). "TCGA data analysis and IHC staining of clinical tumor samples showed that ASNS and CEBPA tended to be underexpressed in the Cluster 2 with poor prognosis." (PMID 35174151, 2022). "Data of expression databases revealed that GLUL and ASNS are overexpressed in HB compared to non-tumor liver tissue." (PMID 34235580, 2021). "ASNS transcription in cancer cells is controlled by tumor-driving oncogenes and elevated in response to amino acid and glucose starvation through adaptive processes known as amino acid and endoplasmic reticulum stress responses." (PMID 33499165, 2021). "ASNS catalyzed the ATP-dependent conversion of aspartate to asparagine, which promoted the proliferation of tumor cells through acting as an amino acid exchange factor." (PMID 35127477, 2021). "Overexpression of ASNS facilitated the growth, metastasis, and chemoresistance of neoplasm cells, and a metabolic vulnerability was shown in specified cancer models with low-ASNS expression." (PMID 35127477, 2021). "ASNS expression in various types of solid tumor cells correlates with higher tumor grade, a propensity to metastasize and poor patient survival." (PMID 33499165, 2021). "We explored this treatment in our mouse model for 1 week, and we did not observe any reduction in tumor volume neither in Glu and Gln levels; however, this short treatment revealed the upregulation of ASNS in tumor tissue." (PMID 33101674, 2020). "As an additional control, we analyzed the tumor levels of Asn in vivo, which provided further evidence of ASNS-knocked out, since Asn concentration was significantly reduced in the KO when compared to the EV group within the vehicle-treated condition." (PMID 33101674, 2020). "In several models of human solid cancers ASNS expression has been found to be positively correlated with tumor growth and, in some cases, chemo-resistance, especially if cis-platinum-derived drugs are involved." (PMID 31998641, 2019). "Consistently, autophagy or ASNS inhibition reduced KRAS-driven tumor cell proliferation, migration, and invasion, all effects rescued by Asn supplementation." (PMID 31998641, 2019). "As an UPR-stimulating gene, ATF6 plays an important role in tumor genesis, and ASNS gene is important in tumor genesis due to its function of synthesis of asparagine, which is an essential amino acid for normal tissue or tumor growth." (PMID 28629319, 2017). "Further tests of ATF6 and ASNS mRNA levels in HCC tumor tissues and corresponding non tumor tissues should be done." (PMID 28629319, 2017).
tumor (continued). "An underlying dependence of CR tumor cells for energy metabolism pathways such as enhanced expression of GLDC, ACC, ASNS, FDFT1, UGDH, PYCR2, etc was noted." (PMID 27470985, 2016). "In acute lymphoblasticleukemia (ALL), hypermethylation of theasparagine synthetase (ASNS) gene promoter, leading to low levelsof ASNS in tumor cells, is recognized as a prognostic biomarker, and l-asparaginase-based treatments (e.g., Asparlas) are frequentlyadministered to these patients." (PMID 40497651, 2025). "In response to Gln deprivation, tumor cells boost asparagine synthesis by upregulating asparagine synthetase (ASNS), allowing aspartate to be converted into asparagine to replenish TCA cycle intermediates and support nucleotide and protein biosynthesis despite Gln limitation." (PMID 40641572, 2025). "ASNS, an enzyme involved in asparagine metabolism, plays a crucial role in the synthesis of asparagine within cells, which is vital for the growth and development of tumor cells." (PMID 40781327, 2025). "In addition, combination therapy involving the depletion of extracellular asparagine (e.g., ASNase) and AKT inhibition decreased tumor growth, suggesting that ASNS can be a promising therapeutic target for KRAS-driven NSCLC." (PMID 39796613, 2025). "Furthermore, ASNS expression in tumor cells at the primary tumor site was positively correlated with the percentage of pathological response." (PMID 41208878, 2025). "Deletion of ASNS caused a reduction in tumor asparagine levels and there was no sex difference in asparagine levels after the gene deletion." (PMID 38886847, 2024). "To target this metabolic fragility unique to the late-stage adenocarcinoma cells, we used 2-deoxy-d-glucose (2-DG) – a glucose analogue and glycolysis inhibitor – as a means of preventing compensatory glucose shuttling and further inhibiting tumour cell proliferation mediated by ASNS knockdown." (PMID 39332495, 2024). "We speculated that STM2457 affected the tumor promotion effect of ASNS by affecting the expression level of ASNS." (PMID 39132158, 2024). "Validation of the transcriptomic changes in the larger mice cohort which included both male and female xenograft mice (n = 8–10 mice per group) showed that ASNS was significantly downregulated in the HCT116 ASNS−/− tumor xenografts from male and female R2G2 mice." (PMID 38886847, 2024). "Moreover, the inhibition of AKT can suppress ASNS expression and depletion of extracellular asparagine, subsequently inhibiting tumor growth." (PMID 37732314, 2023). "Inhibition of ASNS expression and subsequent asparagine depletion may reduce the proliferative capacity of tumor cells." (PMID 35736499, 2022). "ASNS was an essential enzyme for asparagine products, asparagine was a key metabolite in the cellular response to mitochondrial dysfunction and coupled mitochondrial respiration for tumor growth." (PMID 35739087, 2022). "After knockdown of ASNS, the growth of primary tumor could be supported by extracellular asparagine uptaking, but cell invasiveness was impaired by double aspects: limited asparagine and asparagine-independent dysfunctions." (PMID 35739087, 2022). "The microenvironmental concentration of asparagine may limit the flux of aspartate/glutamine through ASNS, severely questioning the relevance of ASNS expression as a marker to predict tumor response to treatment." (PMID 35857457, 2022). "However, further research is necessary on the transcriptional regulation mechanisms of ASNS, also its effect on glutamine metabolism, and its correlation with tumor recurrence and metastasis need to be figured out." (PMID 34540668, 2021).
tumor (continued). "ASNS, GLS, and GOT2 encode ASNS, GLS, and GOT2, respectively, which are key enzymes in asparagine synthesis and are all required for tumor growth and metastasis, prompting the hypothesis that asparagine synthesis is required for SOX12-mediated CRC progression." (PMID 30858360, 2019). "One might hypothesize that ASNS, asparaginase, and autophagy exist in a fine balance that maintains control of asparagine homeostasis in tumor cells." (PMID 31681605, 2019). "On the other hand, although Zhang’s work showed ASNS was higher expressed in HCC tumor tissue, ASNS seemed to have antitumor effect, for patients with low ASNS expression levels had a poor prognosis and ASNS significantly inhibited the proliferation, migration and tumourigenicity of HCC cells." (PMID 28629319, 2017). "Therefore, examination of the effect of E2 on GPER1 and ASNS could help understand the link between sex sex-related factors that may affect ASNS-expressing tumor cells and attenuated tumor growth in females." (PMID 38886847, 2024). "Given that our pathway analyses of both metabolite and transcriptomics data showed a reduction of AMPK, an important mediator of nutrient supply, it is evident that ASNS knockout in female tumors has a marked decrease in nutrient supply that may be affecting tumor growth." (PMID 38886847, 2024). "Thus, inhibition of ASNS expression and consequent consumption of asparagine may reduce the proliferative capability of tumor cells." (PMID 34540668, 2021). "Thus, ASNS overexpression can promote tumor growth under nutrient stress." (PMID 32174781, 2020). "However, ASNS+ and shFLNA promoted and attenuated tumor growth, respectively." (PMID 31681605, 2019). "Notably, ASNS expression in human tumours strongly correlates with expression of genes involved in serine/glycine synthesis and one-carbon metabolism, suggesting that cellular demand for serine and asparagine may be specifically connected." (PMID 27126896, 2016). "As normal asparagine concentrations in mouse and human plasma were previously reported to be between 3.8 mg/L and 7.3 mg/L, these data suggest that freely available asparagine in mouse serum and tissue might counteract the effects of tumor-specific ASNS silencing." (PMID 26499495, 2015). "Interestingly, qualitative assessment of the tumors showed there was desmoplasia (defined as a band of fibrous tissues intermixed within the tumor sheet) observed within the tumor stroma in the HCT116 ASNS+/+ group which may be accounted for by a host response to the expanding viable tumor mass." (PMID 38886847, 2024). "Similar to our initial xenograft in female mice only (tumorigenicity study 1), tumor volume was significantly different between the HCT116 ASNS−/− female and HCT116 ASNS+/+ female mice (1.4-fold, q < 0.05) at 18 days post-implantation." (PMID 38886847, 2024). "Asparagine synthetase (ASNS) is an important target gene of ATF4 that modulates protein synthesis, promotes tumor growth and suppresses cell death." (PMID 39261452, 2024). "To validate our predicted tumor-promoting role of ASNS in PRAD, we knocked down ASNS expression in PC-3 cells using siRNA and overexpressed ASNS in DU145 with the ov-ASNS vector." (PMID 38206293, 2024). "The expression levels of SMS, ASNS, PLOD2, P4HA1, PAH, and KYNU were upregulated in tumor samples compared with normal samples, and the remaining three genes were downregulated." (PMID 37511510, 2023). "Results showed that in Group 1, the protein level of ASNS and CEBPA was higher in tumor tissues than in adjacent normal colon tissues, while in Group 2, the results were opposite." (PMID 35174151, 2022). "Based on accumulating evidence, ASNS, GOT2, and GLS, as well as asparagine, substantially contribute to tumor growth and metastasis." (PMID 30858360, 2019).